ENSG00000252778
Synonyms: LOC124900315
Gene: Small Cajal body-specific RNA gene on chromosome 11 (8,555,016 to 8,555,146, forward strand). Ensembl gene ENSG00000252778.
Gene Ontology:
Biological process: RNA processing
Cellular component: Cajal body; nucleolus
Homologues: Paralogues in human: SCARNA20 (75% identical).